CTLA4 (cytotoxic T-lymphocyte associated protein 4)
Diseases named in the same sentence as CTLA4 in open-access papers (continued):
Sharing a sentence is not in itself a finding about the gene and the disease.
prostate tumors (10 papers, 2013 to 2026). "Tumor control was then rescued through Treg depletion using an anti-CTLA4 antibody, evidencing the significant impact of Tregs on the tumor radiobiology of these prostate tumors." (PMID 40475779, 2025). "Triple combination of IL-15 with antibodies to PD-L1 and CTLA-4 increased antitumor efficacy and prolonged survival of mice with colon and prostate tumors compared to monotherapies." (PMID 37465665, 2023). "In one cohort, anti-CTLA-4 increased expression of PD-1 and VISTA inhibitory checkpoints in prostate tumors, which makes targeting CTLA-4, PD-1, and VISTA an appealing combinatorial approach." (PMID 32117295, 2020). "Determining which patients have hypermutated prostate tumors may have important implications for future precision oncology trials, as mutational burden has been shown to correlate with response to immune checkpoint blockade in several tumor types (e.g. anti-CTLA4, anti-PD1, anti-PDL1)." (PMID 27756888, 2016). "Taken together, these data show that GVAX vaccination induces a detectable, but relatively blunted CD8 T cell response in prostate tumor-bearing mice, and this blunted response correlates with CTLA-4 expression on specific T cells, especially in the target organ." (PMID 23557194, 2013). "have shown that antibodies for PD-1, CTLA-4, and 4-1BB combined with a STING agonist can lead to bilateral tumor regression in 75% of mice with subcutaneous prostate tumors." (PMID 37465665, 2023).
rash (10 papers, 2013 to 2024). "For chemotherapy alone, PD-1 or PD-L1 together with CTLA-4 (Group I), or together with chemotherapy on this basis (Group J), would significantly increase the risk of developing rash." (PMID 35898927, 2022). "The combined use of anti-PD-1 and anti-CTLA-4 antibodies tended to be associated with a higher grade of rash." (PMID 33673164, 2021). "Grade 3 rash was observed in patients receiving anti-PD-1 therapy (n = 4) and combined anti-PD-1 and anti-CTLA-4 therapy (n = 2)." (PMID 33673164, 2021). "Skin rash is the most frequent irAE (15% in anti-PD1, 25% in anti-CTLA4 and 40% in combination); erythematous unspecific self-limited exanthema can appear very early, but the most specific irAE consists of a lichenoid exanthema." (PMID 33228219, 2020).
thyrotoxicosis (10 papers, 2017 to 2025). A hypermetabolic syndrome caused by the elevation of thyroid hormone levels in the serum. "Thyrotoxicosis accounts for 12% of endocrine irAEs and is reported to be more frequently caused by anti-PD-1 antibodies than by anti-CTLA-4 antibodies." (PMID 38910605, 2024). "More specifically, thyrotoxicosis induced by anti-CTLA-4 affects 0.2–1.7% of the patients, while thyrotoxicosis induced by anti-PD-1 affects o.6-3.7% of the patients." (PMID 38345684, 2024). "Conversely, the occurrence of thyrotoxicosis is reported to be lower, with incidence rates ranging from 0.2%-5.2% for anti-CTLA4 therapy, 0.6%-3.7% for anti-PD-1/PDL1 therapy, and between 8% and 11.1% for combination therapy." (PMID 37779728, 2023). "In the literature, initially only induced Graves’ orbitopathy (GO) without thyrotoxicosis were described in patients undergoing Ipilimumab (anti-CTLA-4) treatment." (PMID 33920721, 2021).
acute lymphoblastic leukemia (9 papers, 2012 to 2024). Leukemia with an acute onset, characterized by the presence of lymphoblasts in the bone marrow and the peripheral blood. "Combining the results of the present study with our previous finding, we found that rs11571315 and rs16840252 of CTLA4 were associated with the adverse reaction of post-haematopoietic stem cell transplantation in patients with acute lymphocytic leukemia and immune thrombocytopenia." (PMID 36389676, 2022). "Blocking immune checkpoint regulators such CTLA-4 and PD-1/PD-L1 pathway in solid tumors, as well as customized T cell therapy in acute lymphoblastic leukemia (ALL), cancer immunotherapy, as a monotherapy or in combination with other treatments, has recently ushered in a new age." (PMID 35744922, 2022). "In acute lymphoblastic leukemia (ALL) and bladder cancer, knocking out CTLA-4 augmented recognition by T cells." (PMID 35410257, 2022).
autoimmune hepatitis (9 papers, 2016 to 2023). Hepatitis caused by autoantibodies. "Furthermore, Ctla4 gene polymorphism is a risk factor for drug induced liver injury and is associated with autoimmune liver diseases including primary biliary cirrhosis." (PMID 26934552, 2016). "In autoimmune liver disease, MAIT cells are also found to be exhausted with less IFNγ production and upregulation of PD-1 and CTLA-4 is seen in autoimmune liver disease and hepatitis B infection." (PMID 31627733, 2019). "Here we describe a heterozygous de novo missense variant of CTLA4 in a young girl with childhood-onset autoimmune hepatitis and polyarthritis, the latter responding to treatment with CTLA-4-Ig fusion protein." (PMID 31396201, 2019). "Finally, the 3 genotypes of the CTLA-4 gene were compared between individuals with autoimmune hepatitis and controls." (PMID 36875506, 2023). "In autoimmune hepatitis (AIH), some of the VDR and CTLA4 variants are involved in triggering the immune process, these genotype variants being linked with fatty acid synthase (FAS) promoter variants or pro-inflammatory cytokines that are part of the TNF superfamily." (PMID 36077185, 2022).
chordoma (9 papers, 2021 to 2025). Chordomas are rare malignant tumors arising from embryonic remnants of the notochord in axial skeleton. "The exploration of CTLA-4 and mTOR inhibitors also underlines the diverse strategies being pursued to address the complexity of chordoma pathogenesis." (PMID 38731241, 2024). "Higher expression of CTLA-4 on chordoma tumor tissue was associated with decreased disease-free survival and overall survival, and higher CTLA-4 expression on TIL was associated with decreased disease-free survival only." (PMID 34067530, 2021). "A phase II trial (NCT04416568) is currently recruiting patients to investigate the combination of nivolumab (anti-PD1) with ipilimumab (anti-CTLA4) in children and young adults with SMARCB1-deficient tumours, including RTs, epithelioid sarcomas, and chordomas." (PMID 40422882, 2025). "This study reveals a complex immune microenvironment in chordoma, characterized by elevated immune checkpoint expression (e.g., PD-1, CTLA-4), a highly immunogenic subtype (Cluster 1), and a T cell-centric regulatory network with CCR7 as a key modulator." (PMID 40386066, 2025). "At present, there were two Phase II clinical trials (NCT04416568, NCT02834013) of PD-1 inhibitors and CTLA-4 inhibitors in the treatment of chordoma ongoing, and the efficacy of them was yet to be reported." (PMID 38983929, 2024). "One of the primary ways in which chordoma lesions exhibit immunosuppression is through the identification of CTLA4 and PDCD1 expression on Tregs." (PMID 37784253, 2023). "In 2020, He analyzed 32 specimens of chordoma and found that CTLA-4 showed positive expression on the surface of tumor cells and TILs in all cases." (PMID 37720221, 2023). "A variety of immunosuppressive checkpoints such as PD-1/PD-L1, CD47/SIRPα, TIM3, and CTLA4 are expressed on the surface of both chordoma cells and immune cells, and ICIs are the most widely performed strategy in the field of chordoma immunotherapy." (PMID 37720221, 2023). "Few clinical data are available to demonstrate the advantages of CTLA-4 ICIs combined with PD-1/PD-L1 ICIs over monotherapy in treating chordoma, and ICIs combination therapy shows more toxicity than monotherapy." (PMID 36612259, 2022). "The high expression of PD-1 and CTLA-4 in our chordoma samples suggests that these tumors may be particularly adept at exploiting these pathways to evade immune surveillance." (PMID 40386066, 2025). "We hypothesize that chordoma exhibits elevated expression of key immune checkpoints, such as PD-1 and CTLA-4, compared to normal tissue." (PMID 40386066, 2025). "CTLA-4 antibody was only used as combination therapy in chordoma." (PMID 36612259, 2022). "We found that CTLA-4 ICIs were only used in combination therapy in chordoma." (PMID 36612259, 2022). "One study has identified that CTLA-4 is expressed in a significant portion of chordomas." (PMID 34067530, 2021). "CTLA-4 is also expressed in a significant portion of chordomas, both on TIL and tumoral tissue." (PMID 34067530, 2021). "Despite the elevated proportion of Tregs observed in recurrent chordomas, the cells exhibited significant expression of TIGHT, CTLA4, PDCD1, ENTPD1 and HAVCR2, indicating the immunosuppressive nature of Tregs." (PMID 37784253, 2023). "In addition, studies have shown that the expression levels of CTLA-4 and TIM3 are both high in chordoma, and their expression is related to the invasiveness and recurrence of chordoma." (PMID 37720221, 2023).
diffuse large B-cell lymphoma (9 papers, 2017 to 2025). "A study of m5C in diffuse large B-cell lymphoma has identified a correlation between m5C-affected genes and the modulation of immune checkpoint genes, specifically CTLA-4 and PD-L1." (PMID 39372415, 2024). "eTregs were recently revealed using dual immunostaining of FOXP3 and CTLA4 in diffuse large B cell lymphoma." (PMID 35438346, 2022). "Recently, eTregs were identified in diffuse large B cell lymphoma using dual immunostaining of FOXP3 and CTLA4." (PMID 35438346, 2022).
enteritis (9 papers, 2016 to 2025). Inflammation of the small intestine. "More importantly, cancer patients with a higher abundance of Rikenellaceae undergoing anti-CTL4 therapy were less likely to suffer from CTLA-4-associated enteritis." (PMID 33506015, 2021). "Regarding irAE enterocolitis due to ICI administration, the frequency of enteritis complications has been reported at 18%–23% when anti‐CTLA‐4 antibodies and anti‐PD‐1 inhibitors are used in combination; this tends to be higher than when antibodies are used alone." (PMID 39467776, 2024). "Finally, the SBM-induced enteritis was associated with the transcriptomic activation of T cells by alteration of pathways related to CD28 signalling and CTLA4 signalling, as well as modification of the T cell receptor signalling pathway." (PMID 26925977, 2016).
Hyperglycemia (9 papers, 2019 to 2026). An increased concentration of glucose in the blood. "The reduction in CTLA-4+ Tregs in hyperglycemia coincided with a metabolic shift marked by decreased GLUT1 expression and overall downregulation of mTOR phosphorylation." (PMID 41597269, 2026). "Recent research has demonstrated that hyperglycemia-driven metabolic stress directly impairs immune checkpoint pathways, including PD-1, PD-L1, CTLA-4, TIM-3, and LAG-3, by altering T-cell bioenergetics, mitochondrial function, and redox balance." (PMID 41463504, 2025). "Hyperglycemia-driven suppression of the PD-1/PD-L1 and CTLA-4 pathways leads to persistent T cell activation, regulatory T cell failure, and endothelial barrier instability, creating an ideal environment for vascular inflammation and plaque progression." (PMID 41463504, 2025). "This study reveals that hyperglycemia during treatment with ipilimumab, a CTLA-4 blocking agent, increased cardiotoxicity and reduced mortality of MCF-7 and MDA-MB-231 cells in a manner that is sensitive to NLRP3." (PMID 33096896, 2020). "Furthermore, the amount of total and phosphorylated mTOR, which is directly correlated with glucose metabolism, and CD39+ Tregs, representing the metabolism of ATP into immunomodulatory adenosine, also dropped along with CTLA-4-positive Tregs in hyperglycemia." (PMID 41597269, 2026). "Also, there is experimental study shown that hyperglycemia increased cardiomyocyte damage during anti-CTLA4 ICI (Ipilimumab) administration." (PMID 35096992, 2021). "Accordingly, symptoms of acute hyperglycemia were frequent in our cohort and 21 (62%) presented with DKA (nine of these were receiving combination regimens: six with anti-CTLA4, and three with other agents)." (PMID 35008256, 2021). "There was also an association between hyperglycemia and a reduced percentage of CTLA-4+ Tregs but not CTLA-4+ Tconvs." (PMID 41597269, 2026). "Interestingly, hyperglycemia in in vitro cultures reduced percentages of TIGIT+ Tregs and TIGIT+ Tconvs, and to some extent also CTLA-4+ Tregs." (PMID 41597269, 2026). "Under persistent inflammatory stimuli (e.g., MTB infection combined with hyperglycemia), sustained NF-κB/MAPK hyperactivation may trigger negative feedback mechanisms, such as upregulating inhibitory receptors (e.g., PD-1 and CTLA-4) or Tregs, thereby suppressing effector T-cell function." (PMID 40284755, 2025).
IPEX syndrome (9 papers, 2017 to 2025). "Two children with immunoregulatory disorders (CTLA4 deficiency and IPEX syndrome) experienced disease relapse and required prolonged immunosuppressive therapy." (PMID 37779531, 2023).
liver fibrosis (9 papers, 2013 to 2025). "This suggests the involvement of lymphocytes expressing CTLA-4 as a mechanism to control the inflammatory process associated to liver fibrosis during chronic schistosomiasis." (PMID 24348679, 2013). "In one of our first studies on this topic, we demonstrated that an initial 11 weeks lasting infection with female worms resulted in cytotoxic T-lymphocyte-associated protein 4 (CTLA-4)-mediated reduction of egg-induced hepatic fibrosis of a challenge infection." (PMID 36923416, 2023). "Moreover, we recently reported that single-sex infection with female S. mansoni cercariae mitigates hepatic fibrosis after secondary infection, which was associated with an increased expression of CTLA-4 in these mice." (PMID 31950032, 2019). "Since preventive CTLA-4-Ig treatment was capable to reduce hepatic fibrosis during schistosomiasis, we further analyzed the impact of the treatment on disease progression." (PMID 31950032, 2019). "Overall, these data demonstrate that preventive CTLA-4-Ig administration efficiently ameliorates hepatic fibrosis of S. mansoni-infected mice." (PMID 31950032, 2019). "Based on these data, it was obvious for us to investigate the potential direct antifibrotic effect of CTLA-4 on S. mansoni-induced hepatic fibrosis by mimicking the effect of female worms." (PMID 31950032, 2019). "Under an increased tumour burden (1 × 106 implanted cells), where parallel tumour growth was induced in both groups, mice with CCl4‐induced advanced liver fibrosis showed both a delayed and weakened anti‐tumour response upon treatment with anti‐PD‐1 and anti‐CTLA‐4 immunotherapy." (PMID 40760842, 2025). "The question remains whether the effect of belatacept on CD4+ T cell response in regard to the reduction of hepatic fibrosis is restorable in case of a CTLA-4-Ig treatment stop." (PMID 31950032, 2019). "Based on these findings, we hypothesized that administration of agonistic CTLA-4-Ig (Belatacept) is capable to prevent and/or treat hepatic fibrosis during schistosomiasis." (PMID 31950032, 2019). "We could demonstrate that an early preventive administration of CTLA-4-Ig suppresses effector T cell function and therefore ameliorates liver fibrosis." (PMID 31950032, 2019). "Then we speculate that immune checkpoints might correlate with HSC activation and liver fibrosis and found that SLC1A5 was significantly negatively associated with CTLA4, LAG3, and PDCD1; similarly, SLC7A5 was significantly negatively associated with CTLA4 and LAG3." (PMID 39698464, 2024). "If therapy was started at a later time point when fibrogenesis was initiated, CTLA-4-Ig had no impact on hepatic fibrosis." (PMID 31950032, 2019). "We herein demonstrated that preventive, but not therapeutic, CTLA-4-Ig treatment ameliorated hepatic fibrosis." (PMID 31950032, 2019). "CTLA-4-Ig administration after onset of egg production fails to treat hepatic fibrosis." (PMID 31950032, 2019). "However, our data show that early preventive CTLA-4-Ig treatment ameliorates liver fibrosis, but was not sufficient to treat ongoing fibrotic processes." (PMID 31950032, 2019). "As shown recently, blocking Ctla4 during the acute stage of Schistosoma infection results in an exaggeration of TH2 response, suggesting that high levels of Ctla4 might be involved in a reduction of TH2 response and of hepatic fibrosis." (PMID 28542175, 2017). "However, CTLA-4-Ig administration was not capable to treat ongoing hepatic fibrosis." (PMID 31950032, 2019).
lung squamous cell carcinoma (9 papers, 2016 to 2025). "Similar immunomodulatory roles of DLX2 have been reported in lung squamous cell carcinoma, and DLX2 was found to be associated with the IPS of PD-1/PD-L1 blockade as well as CTLA-4 combined with PD-1/PD-L1 blockade." (PMID 41244921, 2025). "In lung squamous cell carcinoma, 38 genes were identified for CTLA4, 20 genes for CD274 expression." (PMID 27683114, 2016). "In order to learn more about the connection between CPT2 and immunotherapy, we discovered that patients with lung squamous cell carcinoma who received anti-PDL1 and anti-CTLA-4 treatment had higher survival rates when CPT2 was highly expressed." (PMID 37251324, 2023). "It was demonstrated that survival in squamous cell lung cancer was significantly increased when CPT2 was highly expressed and treated with anti-PDL1 or anti-CTLA-4." (PMID 37251324, 2023). "In lung squamous cell carcinoma, YTHDF1 is significantly negatively correlated with PD-L1, PD-1, PD-L2, CTLA-4, TIGIT, VISTA, and TIM3." (PMID 36479088, 2022).
Lymphadenopathy (9 papers, 2009 to 2023). Enlargement (swelling) of a lymph node. "Although immunotherapy (CTLA-4, PD-1/PD-L1) has been associated with sarcoid-like pulmonary changes including lymphadenopathy, radiographic imaging can present with varied radiographic findings." (PMID 30719394, 2018). "Hepatosplenomegaly and/or lymphadenopathy was mainly found in the patients with LCH, metabolic diseases (such as MMA and Niemann-Pick disease (NPD)), PID associated ILD (such as CVID, CTLA4 deficiency, ALPS and CGD) and malignant infiltrates." (PMID 31969166, 2020). "Ctla4-/- mice die by 3-4 weeks of age, with lymphadenopathy and splenomegaly, consisting of T cell expansions expressing activation markers, and lymphocytic infiltration and tissue destruction of many organs, including heart and pancreas." (PMID 19951419, 2009). "CTLA-4 knockout mice have a massive, CD28-dependent expansion of autoreactive T-cells and die within 3 to 4 weeks due to extensive lymphoproliferation and lymphadenopathy, evidence of the significant role CTLA-4 plays in inhibiting the activation and proliferation of T-cells." (PMID 23738073, 2013).
neuroendocrine tumors (9 papers, 2020 to 2026). "Immunotherapy with checkpoint inhibitors targeting the programmed cell death protein 1 (PD-1)/programmed death-ligand 1 (PD-L1) axis or Cytotoxic T-lymphocyte-associated protein 4 (CTLA-4) has shown only modest activity in neuroendocrine tumors (NET) and neuroendocrine carcinomas (NEC)." (PMID 33228231, 2020). "Recent advancements in tumor immunotherapy, particularly antibodies targeting CTLA-4 and PD-1/PD-L1, have effectively treated various cancers, including neuroendocrine tumors." (PMID 41657564, 2026). "Other immune checkpoint ligand molecules, such as CTLA-4, galectin-9 and CD155, have been investigated in some neuroendocrine tumors and their expression has been associated with better prognosis and response to immune checkpoint inhibitors." (PMID 34208144, 2021). "The aggressive neuroendocrine tumor biology of SCLC may increase CTLA-4 expression as a means of suppressing T cell-mediated immunity." (PMID 39941799, 2025). "The average number of participating centers per trial was 56, with the highest number 1,013 centers, reported in the Dual Anti-CTLA-4 and Anti-PD-1 Blockade in Rare Tumors (DART) study targeting neuroendocrine tumors." (PMID 41225614, 2025).